PFKL (phosphofructokinase, liver type)
Description:
Catalyzes the phosphorylation of D-fructose 6-phosphate to fructose 1,6-bisphosphate by ATP, the first committing step of glycolysis. Negatively regulates the phagocyte oxidative burst in response to bacterial infection by controlling cellular NADPH biosynthesis and NADPH oxidase-derived reactive oxygen species. Upon macrophage activation, drives the metabolic switch toward glycolysis, thus preventing glucose turnover that produces NADPH via pentose phosphate pathway (By similarity).
Synonyms: ATP-PFK; PFK-L; PFK-B
Tractability: Small molecule: a structure with a bound ligand is known. Antibody: its Gene Ontology location is reachable by antibodies, with high confidence. PROTAC: ubiquitination databases record sites on it; its protein half-life has been measured.
Target class: Enzyme
Gene: Protein-coding gene on chromosome 21 (44,300,017 to 44,327,377, forward strand). Ensembl gene ENSG00000141959.
Subcellular location: Cytoplasm
Subcellular location (Human Protein Atlas): Mitochondria; Nucleoli
Pathways (Reactome):
Immune System: Neutrophil degranulation
Metabolism: Glycolysis
Gene Ontology:
Molecular function: 6-phosphofructokinase activity; ATP binding; fructose binding; fructose-6-phosphate binding; identical protein binding; kinase binding; protein binding; monosaccharide binding
Biological process: fructose 1,6-bisphosphate metabolic process; fructose 6-phosphate metabolic process; glycolytic process; response to glucose; canonical glycolysis
Cellular component: 6-phosphofructokinase complex; cytosol; extracellular exosome; membrane; extracellular region; ficolin-1-rich granule lumen; secretory granule lumen; cytoplasm
Genetic constraint (gnomAD): Loss-of-function variants: 68 observed, 80.94 expected, observed/expected ratio (o/e) 0.84, 90% interval 0.69 to 1.03. The upper end of that interval is the gene's LOEUF score, 1.03, which puts it in group 4 of 6, group 1 being the genes least tolerant of losing a copy. Missense variants: 974 observed, 1,040.7 expected, observed/expected ratio (o/e) 0.94, 90% interval 0.89 to 0.99. Synonymous variants: 464 observed, 421.99 expected, observed/expected ratio (o/e) 1.1, 90% interval 1.02 to 1.19.
Homologues: Orthologues: chimpanzee PFKL (100% identical), macaque PFKL (99% identical), mouse Pfkl (94% identical), rat Pfkl (94% identical), dog PFKL (91% identical), guinea pig PFKL (91% identical), pig PFKL (82% identical), zebrafish pfklb (80% identical), zebrafish pfkla (78% identical), Drosophila melanogaster Pfk (56% identical), Caenorhabditis elegans pfk-1.1 (56% identical). Paralogues in human: PFKM (69% identical), PFKP (68% identical).
Diseases named in the same sentence as PFKL in open-access papers:
PFKL is named in the same sentence as 42 diseases in open-access papers, as found by Europe PMC text mining. Sharing a sentence is not in itself a finding about the gene and the disease. The quoted sentences say what the papers report.
hepatocellular carcinoma (12 papers, 2020 to 2025). A malignant tumor that arises from hepatocytes. "We have previously shown that mutation of asparagine 702 to threonine renders PFKL unable to form filaments in vitro and assemble into condensates in human HepG2 hepatocellular carcinoma cells." (PMID 41159217, 2025). "Overall, DNAAF5 serves as a scaffold protein to recruit USP39 to form a ternary complex by directly binding the PFKL protein, thereby improving the stability of the latter, which promotes the malignant process of hepatocellular carcinoma." (PMID 36276075, 2022). "A number of cancers have been identified to have PFKL as a component of the glycolysis process, including lung cancer, esophageal cancer, neuroblastoma and hepatocellular carcinoma." (PMID 35924146, 2022). "Additionally, recent evidence in hepatocellular carcinoma cells suggests that glucose starvation promotes the phosphorylation of PFKL, which facilitates its binding to Plin2." (PMID 40825999, 2025). "However, other ubiquitin ligases, TRIM21 and A20, have been reported to catalyse ubiquitination-mediated degradation of PFKP in glioblastoma and PFKL in hepatocellular carcinoma." (PMID 35670764, 2022). "In hepatocellular carcinoma (HCC), PFKL was degraded by interaction with A20 and suppressed the progression of HCC." (PMID 34368128, 2021). "This has recently been explored in hepatocellular carcinoma (HCC), in which the E3 ubiquitin ligase A20 usually acts as a tumour suppressor by targeting PFKL for degradation." (PMID 40329473, 2025). "In hepatocellular carcinoma, YTHDF3, a m6A “reader”, inhibits the degradation of PFKL mRNA by m6A modification, and promotes the expression of PFKL and aerobic glycolysis." (PMID 37582735, 2023).
lung carcinoma (8 papers, 2018 to 2023). "PFKL is associated with the predicting poor overall lung cancer patient survival." (PMID 37576511, 2023). "In lung cancer, overexpression of PFKL (phosphofructokinase) has been found to promote cell growth, colony formation, and decrease cellular ATP content, while also predicting poor overall survival." (PMID 37576511, 2023). "The regulation of PFKL resulted in a metabolic shift from glycolysis to oxidative phosphorylation (OXPHOS) in lung cancer cells." (PMID 36013278, 2022). "In NCI-H460 lung cancer cells, phosphofructokinase liver type (PFKL) was known to be regulated by the miR-128–PFKL–AKT axis." (PMID 36013278, 2022). "Furthermore, we discovered that miR-128-3p directly targets PFK liver type (PFKL) in lung cancer cells and regulates endogenous expression of PFKL at both mRNA and protein levels." (PMID 30420640, 2018). "Moreover, elevated expression of PFKL or TAp73 significantly correlated with poor prognosis of lung cancer patients." (PMID 30409970, 2018).
breast carcinoma (7 papers, 2013 to 2025). "Collectively, our findings provide insight into the function of PFKL in chemotaxing breast cancer cells." (PMID 41159217, 2025). "Here, we investigated the role of the liver isoform of the ‘gatekeeper’ glycolytic enzyme phosphofructokinase-1 (PFKL) in breast cancer cell migration." (PMID 41159217, 2025). "We have observed the localization of PFKL to lamellipodia of migrating breast cancer cells, where it colocalized with hexokinase-2 and pyruvate kinase M2." (PMID 41159217, 2025). "In this study, we investigate the requirement of PFKL in directional migration of MDA-MB-231 triple-negative human breast cancer cells to better understand how PFKL localization within the cytoplasm supports its function." (PMID 41159217, 2025). "Together, these data show that PFKL is required to sustain directional migration in breast cancer cells." (PMID 41159217, 2025). "show that hypoxia-related features of PFKL gene can serve as a potential biomarker for the prognosis of breast cancer." (PMID 39669558, 2024). "HMGB3, XRCC4, RGS3 and PFKL have been identified as potential target genes for breast cancer in many studies, providing more directions for the treatment of breast cancer patients." (PMID 39669558, 2024). "Here, we asked whether PFKL is required for chemotaxis in the human breast cancer cell line MDA-MB-231." (PMID 41159217, 2025). "PFKL has also been shown to play an essential role in tumorigenesis, with its up-regulation promoting tumor cell proliferation and metabolic reprogramming in various cancers, such as glioma and breast cancer." (PMID 34819091, 2021). "Though there were no specific studies demonstrating the relationship between ALDOA/PFKL/PGK1 and TNBC, a previous study reported that aerobic glycolysis is crucial for modulating breast cancer cell proliferation, invasion, migration, and metastasis both in vitro and in vivo." (PMID 34490098, 2021). "Our investigation also revealed that other isoforms of phosphofructokinase, i.e., PFKL and PFKM, do not play important roles in promoting breast cancer progression as only high PFKP gene expression is associated with poor survival in breast cancer patients." (PMID 29069720, 2017).
glioma (4 papers, 2017 to 2022). A benign or malignant brain and spinal cord tumor that arises from glial cells (astrocytes, oligodendrocytes, ependymal cells). "Our data firstly showed that the glycolysis process and the expression of glycolytic enzymes, HK-2 and PFKL) in glioma cells were suppressed upon the knockdown of UBE2D3." (PMID 34195079, 2021). "Most cellular metabolism genes investigated in glioma cell lines (ATP5A1, COX5A, CPT2, PFKL, and UQCRFS1) were found to be statistically downregulated." (PMID 36142793, 2022).
esophageal cancer (3 papers, 2022 to 2024). A primary or metastatic malignant neoplasm involving the esophagus. "Recently, utilizing the Drug affinity response target stability (DARTS) method, researchers have identified PFKL as a direct target of penfluridol, which effectively inhibits glycolysis and suppresses esophageal cancer tumorigenesis." (PMID 38287371, 2024).
liver cancer (3 papers, 2022 to 2024). An epithelial or non-epithelial malignant neoplasm that arises from the liver. "Previous studies have shown that the ubiquitin E3 ligase A20 mediates the ubiquitination of PFKL, which marks it for degradation—leading to the suppression of tumor growth in liver cancer cells." (PMID 38388430, 2024). "Surprisingly, PFKL positively regulates the expression of YTHDF3 protein, forming a positive feedback loop of YTHDF3-PFKL-YTHDF3, promoting the growth and lung metastasis of liver cancer." (PMID 37582735, 2023). "The findings illuminated that compared with the blank control (vector), overexpression of lncRNA ZNF674-AS1 inhibited the expression of key proteins HK2, PFKL, PKM2, and GLUT1 in the glycolysis process of liver cancer SMMC-7721 and HepG2 cells." (PMID 35874626, 2022). "Moreover, overexpression of lncRNA ZNF674-AS1 reduces the expression of HK2, PFKL, PKM2, and GLUT1 and inhibits glycolysis of liver cancer cells." (PMID 35874626, 2022). "Herein, it was demonstrated that overexpression of lncRNA ZNF674-AS1 could remarkably inhibit the expression of PFKL, HK2, GLUT1, and PKM2 in the glycolysis metabolism of liver cancer cells." (PMID 35874626, 2022).
neuroblastoma (3 papers, 2021 to 2025). Neuroblastoma (NB) is the most common solid, extracranial childhood tumor. "Furthermore, it induced neuroblastoma cell apoptosis, which was reversed after PFKL‐OE." (PMID 41476787, 2025). "Moreover, PFKL downregulation by siRNA transfection induced apoptosis of neuroblastoma cells." (PMID 41476787, 2025).
bipolar affective disorder (2 papers, 2008 to 2024). "Genetic loci near PFKL have been associated with bipolar affective disorder, but to our knowledge, no SNPs are known to modulate diet response." (PMID 18254975, 2008). "In bipolar disorder, most glycolytic genes were downregulated, which included PFKM, PFKP, and PFKL, providing support for decreased glycolytic flux, but the magnitude of gene expression change was greater among the upregulated genes." (PMID 39125835, 2024).
cardiac hypertrophy (2 papers, 2023 to 2024). "A recent study highlighted the role of the KLF7/PFKL/ACADL axis in regulating myocardial metabolic remodeling during myocardial hypertrophy." (PMID 38347951, 2024). "KLF7 can simultaneously activate and repress the expression of ACADL and PFKL respectively to mediate the pathological progression of cardiac hypertrophy." (PMID 36810848, 2023). "Then, we demonstrate that chronic, persistent induction of PFKL in the heart directly drives cardiac hypertrophy by activating the glycolysis." (PMID 36810848, 2023). "Here, our findings show that PFKL was induced in vivo and in vitro in a cardiac hypertrophy model." (PMID 36810848, 2023). "However, the direct correlation between PFKL expression and cardiac hypertrophy has remained unclear." (PMID 36810848, 2023). "Moreover, cardiac-specific PFKL knockdown improved the pathological phenotype of cardiac hypertrophy in KO mice." (PMID 36810848, 2023). "Thus, to assess whether KLF7 can trigger pathological cardiac hypertrophy by balancing the expression of PFKL and ACADL in vivo, we generated transgenic mice (TG) in a cardiac myocyte-specific manner." (PMID 36810848, 2023). "Then, we sought to determine whether the KLF7/PFKL/ACADL axis regulates cardiac hypertrophy growth." (PMID 36810848, 2023). "Our findings show that KLF7/PFKL/ACADL signaling has been shown to be an essential process for cardiac FAO and glycolysis, leading to cardiac hypertrophy and HF." (PMID 36810848, 2023). "Although we focused on PFKL and ACADL in the present study, it is very likely that the expression of other genes is also controlled by transcriptional programs involving KLF7 to induce cardiac hypertrophy." (PMID 36810848, 2023).
colon cancer (2 papers, 2018 to 2025). "In almost all eight cases, the expression of PFKL was concomitantly increased, while the expression of both TAp73 and PFKL was low in the remaining cases, indicating up-regulation of and positive correlation between TAp73 and PFKL expression in colon cancer." (PMID 30409970, 2018). "Moreover, upon TAp73 knockdown, PFKL protein and/or mRNA levels declined in cervical cancer HeLa cells and colon cancer HCT116 cells." (PMID 30409970, 2018).
oral cancer (2 papers, 2021 to 2023). "Hypoxia related genes NF-κB, HIF1α, HK2, and PFKL were upregulated in CAFs activated by oral cancer-derived EVs." (PMID 37745296, 2023). "Meanwhile, downregulating PFKL promoted NB cell death, consistent with a previous study in which PFKL knockdown significantly suppressed the progression of oral cancer." (PMID 34819091, 2021).
ovarian carcinoma (2 papers, 2021). A malignant neoplasm originating from the surface ovarian epithelium. "In addition, except for phosphofructokinase liver type (PFKL), the expression levels of other indicators that were not confirmed to have high expression in ovarian cancer were slightly darker in ovarian cancer tissues than in normal tissues." (PMID 34277429, 2021).
aplasia cutis congenita (1 paper, 2025). Aplasia cutis congenita (ACC) is a rare skin disorder characterized by localized absence of skin that is usually located on the scalp but can occur anywhere on the body including the face, trunk and extremities. "PFKL, associated with normal hair follicle development and cycle, is a genetic candidate for aplasia cutis congenita." (PMID 41380997, 2025).
colitis (1 paper, 2024). Inflammation of the colon. "Specifically, our results revealed decreased levels of glycolytic enzymes, including HK1, GPI, PFKL, ALDOA, and ALDOB in colitis." (PMID 38668322, 2024). "We observed a reduced relevant abundance for hexokinase (HK1), glucose-6-phosphateisomerase (GPI), phosphofructokinase (PFKL), fructose 1,6-biphosphate aldolase enzymes (ALDOA, ALDOB), triosephosphate isomerase (TPI), phosphoglycerate kinase 1 (PGK1), and alpha enolase (ENO1) in colitis." (PMID 38668322, 2024).
colorectal cancer (1 paper, 2024). A primary or metastatic malignant neoplasm that affects the colon or rectum. "Further experiments revealed that silencing CDKN2A markedly decreased the mRNA levels of the phosphofructokinase genes PFKL and PFKM in colorectal cancer cell lines." (PMID 38888512, 2024).
Hepatic fibrosis (1 paper, 2025). The presence of excessive fibrous connective tissue in the liver. "Depletion of CAV1 attenuates hepatic fibrosis by promoting SQSTM1-mediated PFKL degradation in hepatic stellate cells." (PMID 40303344, 2025).
hyperglycaemia (1 paper, 2023). "In the present study, using HepG2 cells under hyperglycaemia stress as a model, we show that treatment of cells with Cr3+ resulted in significant upregulation of glycolysis enzymes (GCK and PFKL) but downregulation of gluconeogenesis enzymes (G6Pase and PEPCK)." (PMID 36977671, 2023).
kidney cancer (1 paper, 2016). Primary or metastatic malignant neoplasm involving the kidney. "Knockdown of PFKP, but not PFKL or PFKM, inhibited kidney cancer cell growth and induced apoptosis and cell cycle arrest." (PMID 27049827, 2016).
lung adenocarcinoma (1 paper, 2023). A carcinoma that arises from the lung and is characterized by the presence of malignant glandular epithelial cells. "The amplified products were subjected to agarose gel electrophoresis, and six samples all gave clear bands in the correct region indicated by the marker, confirming that the six predicted six-HRGs (STC1, PFKL, HK1, PDK3, SLC2A1, XPNPEP1) were all expressed in lung adenocarcinoma A549 cells." (PMID 37576511, 2023).
rheumatoid arthritis (1 paper, 2023). A chronic, systemic autoimmune disorder characterized by inflammation in the synovial membranes and articular surfaces. "The glycolytic rate limiting phosphofructokinase (PFKL) is essential for ATP generation, autophagy and redox balance in rheumatoid arthritis T cells." (PMID 37629565, 2023).
type 2 diabetes (1 paper, 2016). "Methylation of the ATF-motif in PFKL was observed to be reduced in obese patients compared to non-obese controls in a study investigating epigenetic modifications in terms of the aetiology of type 2 diabetes." (PMID 27559110, 2016).